IGHV1-3 (immunoglobulin heavy variable 1-3)
Description:
V region of the variable domain of immunoglobulin heavy chains that participates in the antigen recognition. Immunoglobulins, also known as antibodies, are membrane-bound or secreted glycoproteins produced by B lymphocytes. In the recognition phase of humoral immunity, the membrane-bound immunoglobulins serve as receptors which, upon binding of a specific antigen, trigger the clonal expansion and differentiation of B lymphocytes into immunoglobulins-secreting plasma cells. Secreted immunoglobulins mediate the effector phase of humoral immunity, which results in the elimination of bound antigens. The antigen binding site is formed by the variable domain of one heavy chain, together with that of its associated light chain. Thus, each immunoglobulin has two antigen binding sites with remarkable affinity for a particular antigen. The variable domains are assembled by a process called V-(D)-J rearrangement and can then be subjected to somatic hypermutations which, after exposure to antigen and selection, allow affinity maturation for a particular antigen.
Synonyms: VI-3B; IGHV13
Gene: Immunoglobulin variable (V) gene on chromosome 14 (106,005,095 to 106,005,574, reverse strand). Ensembl gene ENSG00000211935.
Subcellular location: Secreted; Cell membrane
Gene Ontology:
Molecular function: antigen binding
Biological process: immunoglobulin mediated immune response
Cellular component: extracellular region; plasma membrane
Homologues: Orthologues: chimpanzee IGHV1-3 (82% identical), mouse Ighv1-53 (71% identical), mouse Ighv1-50 (70% identical), mouse Ighv1-74 (70% identical), mouse Ighv1-55 (69% identical), mouse Ighv1-64 (69% identical), mouse Ighv1-66 (68% identical), mouse Ighv1-69 (68% identical), mouse Ighv1-4 (68% identical), mouse Ighv1-52 (67% identical), mouse Ighv1-59 (67% identical), mouse Ighv1-61 (67% identical), and 48 more. Paralogues in human: IGHV1-2 (88% identical), IGHV1-18 (87% identical), IGHV1OR15-1 (86% identical), IGHV1-46 (85% identical), IGHV1-45 (83% identical), IGHV1-58 (83% identical), IGHV1-69 (81% identical), IGHV1-69D (81% identical), IGHV1-24 (79% identical), IGHV7-4-1 (79% identical), IGHV1OR21-1 (79% identical), IGHV1OR15-9 (78% identical), and 65 more.